GPR31 (G protein-coupled receptor 31)
Description:
High-affinity receptor for 12-(S)-hydroxy-5,8,10,14-eicosatetraenoic acid (12-S-HETE), with much lower affinities for other HETE isomers. 12-S-HETE is a eicosanoid, a 12-lipoxygenase (ALOX12) metabolite of arachidonic acid, involved in many physiologic and pathologic processes. 12-S-HETE-binding leads to activation of ERK1/2 (MAPK3/MAPK1), MEK, and NF-kappa-B pathways leading to cell growth. Plays a crucial role for proliferation, survival and macropinocytosis of KRAS-dependent cancer cells by mediating the translocation of KRAS from the endoplasmic reticulum to the plasma membrane (PM) and its association with the PM. Contributes to enhanced immune responses by inducing dendrite protrusion of small intestinal CX3CR1(+) phagocytes for the uptake of luminal antigens (By similarity). Acts also as a key receptor for 12-(S)-HETE-mediated liver ischemia reperfusion injury. Proton-sensing G protein-coupled receptor.
Synonyms: 12-HETER; HETER1; HETER
Tractability: Small molecule: it belongs to a druggable protein family. Antibody: UniProt places it where antibodies can reach, with high confidence; its Gene Ontology location is reachable by antibodies, with high confidence; UniProt predicts a signal peptide or a membrane-spanning region.
Target class: Small molecule receptor (family A GPCR); Lipid-like ligand receptor (family A GPCR); Membrane receptor; Family A G protein-coupled receptor
Gene: Protein-coding gene on chromosome 6 (167,155,247 to 167,157,980, reverse strand). Ensembl gene ENSG00000120436.
Subcellular location: Cell membrane
Pathways (Reactome):
Signal Transduction: Free fatty acid receptors; G alpha (i) signalling events
Gene Ontology:
Molecular function: arachidonate binding; G protein-coupled receptor activity; protein binding; bioactive lipid receptor activity
Biological process: G protein-coupled receptor signaling pathway; response to acidic pH; negative regulation of inflammatory response; response to molecule of bacterial origin; positive regulation of immune response; response to ischemia
Cellular component: plasma membrane; membrane
Genetic constraint (gnomAD): Loss-of-function variants: 1 observed, 0.44 expected, observed/expected ratio (o/e) 2.27. That is too few expected variants to judge how well the gene tolerates losing a copy. Missense variants: 394 observed, 417.63 expected, observed/expected ratio (o/e) 0.94, 90% interval 0.87 to 1.02. Synonymous variants: 209 observed, 193.16 expected, observed/expected ratio (o/e) 1.08, 90% interval 0.97 to 1.21.
Homologues: Orthologues: chimpanzee GPR31 (99% identical), macaque GPR31 (93% identical), dog GPR31 (66% identical), pig GPR31 (62% identical), mouse Gpr31b (61% identical), guinea pig GPR31 (60% identical), rat Gpr31 (60% identical). Paralogues in human: HCAR2 (33% identical), HCAR3 (33% identical), HCAR1 (31% identical), OXER1 (30% identical), P2RY2 (24% identical), P2RY1 (24% identical), SUCNR1 (22% identical), P2RY4 (22% identical), FFAR1 (21% identical), GPR42 (21% identical), OXGR1 (21% identical), P2RY6 (21% identical), and 3 more.
Diseases named in the same sentence as GPR31 in open-access papers:
GPR31 is named in the same sentence as 26 diseases in open-access papers, as found by Europe PMC text mining. Sharing a sentence is not in itself a finding about the gene and the disease. The quoted sentences say what the papers report.
hepatocellular carcinoma (5 papers, 2019 to 2025). A malignant tumor that arises from hepatocytes. "Increasing evidence has suggested that GPR31 plays an important role in diverse pathophysiological processes, such as pancreatic development, atherosclerosis, prostate cancer, hepatocellular carcinoma, platelet activation, and arterial thrombosis." (PMID 40892510, 2025). "In vitro studies also demonstrated that 12-HETE enhanced hepatocellular carcinoma (HCC) cell migration by inducing epithelial-mesenchymal transition (EMT) via activation of GPR31." (PMID 38505262, 2024).
prostate carcinoma (4 papers, 2017 to 2025). A carcinoma that arises from epithelial cells of the prostate gland. "Furthermore, the expression of 12-HETER1 positively correlates with the grades of prostate cancer, and knockdown of GPR31 in cancer cells inhibited HCC recurrence in NAFLD." (PMID 35011589, 2021). "Although we have not detected differences in mRNA expression of the 12-S-HETE biosynthetic proteins, or the 12-S-HETE receptor (GPR31) between winner and loser GSCs, in human prostate cancer expression levels of GPR31 and 12-S-HETE both positively correlate with metastasis." (PMID 37903140, 2023).
melanoma (3 papers, 2018 to 2022). A malignant, usually aggressive tumor composed of atypical, neoplastic melanocytes. "Even though there is little information on the expression of GPR31 in melanomas and NMSC, the role in cancer progression has been proven in other tissues." (PMID 35011589, 2021). "In this study, we investigated the expression profiles of TASK1, TASK3, GPR31 and GPR151 in squamous cell carcinomas (SCCs), basal cell carcinomas (BCCs), nevus cell nevi (NCN), and malignant melanomas (MMs)." (PMID 35011589, 2021). "Interestingly, along these lines, we observed a significant increase in the expression GPR31, along with the phosphorylated forms of PKC and MAPKs, following 12-HETE treatment in HK-2 cells, similar to the increase described in melanoma cells." (PMID 35315361, 2022).
fatty liver (2 papers, 2019 to 2025). "Gpr31 deficiency significantly reduced liver weight as well as the ratio of liver weight to body weight in response to the HFHC diet, accompanied by marked attenuation of hepatic steatosis, inflammatory cell infiltration, fibrosis, and liver injury." (PMID 40892510, 2025).
ischemia (2 papers, 2022 to 2025). A hypoperfusion of the BLOOD through an organ or tissue caused by a PATHOLOGIC CONSTRICTION or obstruction of its BLOOD VESSELS, or an absence of BLOOD CIRCULATION. "GPR31 serves as a high-affinity receptor for 12-HETE; the consensus is that, in the model of hepatic ischemia-reperfusion injury, the effects of 12-HETE are mediated via GPR31." (PMID 35315361, 2022).
colorectal cancer (1 paper, 2021). A primary or metastatic malignant neoplasm that affects the colon or rectum. "GPR31 expression is significantly upregulated in colorectal cancer tissues." (PMID 35011589, 2021). "High GPR31 expression indicates poor prognosis of colorectal cancer." (PMID 35011589, 2021).
lipid metabolic disorders (1 paper, 2025). "RNA-Seq analysis results also clearly showed that MASH-associated genes in lipid metabolic disorders, inflammatory responses, fibrosis, and cell injury were substantially mitigated in the Gpr31-Hep-KO mouse liver tissues compared with the controls." (PMID 40892510, 2025). "In addition, the overall transcriptional profiles of hepatocytes revealed by RNA-Seq analyses further indicated that the N5Q and DNQ mutations abolished the exacerbating effects of GPR31 on changes in genes associated with lipid metabolic disorder, inflammatory responses, and cell injury." (PMID 40892510, 2025).
osteoporosis (1 paper, 2022). A condition of reduced bone mass, with decreased cortical thickness and a decrease in the number and size of the trabeculae of cancellous bone (but normal chemical composition), resulting in increased fracture incidence. "Regrettably, there are currently few studies on GPR31, and studies related to osteoporosis have not been reported." (PMID 36188607, 2022).
skin cancer (1 paper, 2021). "As HCARs play a role in skin cancer and epidermal differentiation, GPR31 could also be involved in skin tumor development." (PMID 35011589, 2021). "We examined the expression profiles of GPR31, GPR151, TASK1 and TASK3 in the most common types of skin cancer." (PMID 35011589, 2021).
skin tumor (1 paper, 2021). "Taking these considerations and our results into account together, GPR31 might serve as a potential diagnostic target, but more functional studies are required to fully understand the role of GPR31 in skin tumor progression." (PMID 35011589, 2021). "We performed immunohistochemistry using paraffin-embedded tissue samples from patients and found that most skin tumors express TASK1/3 and GPR31/151." (PMID 35011589, 2021). "As this is the first study on the expression of these pH-sensitive proteins (GPR31/151, TASK1/3) in skin tumors in the literature, our approach is descriptive." (PMID 35011589, 2021).
steatosis (1 paper, 2025). Increased lipid within the cytoplasm of cells. "Notably, GPR31 overexpression in hepatocytes resulted in the most extensive activation of steatosis-related pathways and was also associated with the most consistent pattern of differentially expressed genes (DEGs) among all candidate GPCRs." (PMID 40892510, 2025).
tumor (9 papers, 2019 to 2024). "In the context of tumor biology, GPR31 was identified to mediate KRAS membrane association and is crucial for proliferation and survival of KRAS-dependent tumors suggesting that GPR31 may represent a target for anti-RAS therapy." (PMID 34440817, 2021). "GPR31 has also been reported to regulate the membrane association of KRAS and play an important role in KRAS-dependent tumor survival and proliferation." (PMID 38505262, 2024). "Studies on cBioportal were analyzed for mutation frequencies of GPR31, GPR151, KCNK3, and KCNK9 in the investigated tumor entities." (PMID 35011589, 2021). "Future research should examine whether protons regulate calcium signaling through GPR31/151 and play a role in tumor progression remains to be investigated." (PMID 38505262, 2024). "GPR31 (G protein-coupled receptor 31) encodes a high-affinity cell membrane receptor for 12-S-HETE, which is an arachidonic acid metabolite secreted by platelets and tumor cells that induces endothelial cell retraction and plays a role in extravasation and metastasis." (PMID 32165663, 2020). "In contrast to these tumor entities, BCCs were negative in ~50% of the samples, which is a striking immunohistochemical feature and similar to the results we found for GPR31, GPR151, TASK1, TASK3 and ASIC2." (PMID 36674553, 2023). "Moreover, the GPR31 dependent EMT and MMPs induced by 12-HETE played an important role in the invasion ability of circulation tumor cells." (PMID 31831037, 2019).
cancer (5 papers, 2019 to 2024). A tumor composed of atypical neoplastic, often pleomorphic cells that invade other tissues. "Furthermore, knockdown of GPR31 in cancer cells inhibited the HCC recurrence in NAFLD." (PMID 31831037, 2019). "The product of 12-lipoxygenase, 12(S)-HETE acts through the G protein-coupled receptor 31 (GPR31), and promotes proliferation and metastasis of cancer cells." (PMID 30897712, 2019).
dermatosis (1 paper, 2020). "Although it was verified that GPR31, a 12(S)-HETE-selective receptor, mediated the function of 12(S)-HETE in dermatosis, the specific function of GPR31 needs to be further investigated in inflammatory macrophages." (PMID 32366266, 2020).
metabolic disorders (1 paper, 2025). "The expression level of GPR31 was significantly correlated with genes and pathways of metabolic disorders, inflammatory response, fibrosis, and cell damage." (PMID 40892510, 2025).
GPR31 also shares sentences with these, for which no sentence is quoted: acute kidney injury (1 paper); adenocarcinoma (1); Arterial thrombosis (1); atherosclerosis (1); basal cell carcinoma (1); breast carcinoma (1); cardiac ischemia (1); gastric cancer (1); Hepatic steatosis (1); squamous cell carcinoma (1); thrombosis (1).